TRPV4 (transient receptor potential cation channel subfamily V member 4)
Diseases named in the same sentence as TRPV4 in open-access papers (continued):
Sharing a sentence is not in itself a finding about the gene and the disease.
parastremmatic dysplasia (2 papers, 2020 to 2022). "Describe TRPV4 mutations in patients with spondylo-epiphyseal dysplasia (SED) and parastremmatic dysplasia." (PMID 35626880, 2022).
pneumonia (2 papers, 2021 to 2022). An acute, acute and chronic, or chronic inflammation focally or diffusely affecting the lung parenchyma, caused by an infection in one or both of the lungs (by bacteria, viruses, fungi, or mycoplasma.). "Furthermore, in an LPS-induced acute lung damage model, blocking TRPV4 function prevented pneumonia and decreased the generation of proinflammatory markers, including IL-6, TNF-α, and ROS." (PMID 36552524, 2022). "Mice lacking TRPV1 or TRPV4 channels, however, showed moderate to severe pneumonia 48 h after the super-infection of the pneumococcus." (PMID 34804016, 2021).
pulpitis (2 papers, 2019 to 2025). Inflammation of the dental pulp. "TRPV4 on neurons has been implicated in mediating pain associated with temporomandibular disorder, pulpitis, and visceral pain, inflammatory conditions in which expression of TRPV4 is upregulated on neurons." (PMID 40144515, 2025). "Recently, one study showed TRPV4 expression in the nerves of human tooth pulps and that TRPV4 expression was upregulated in human tooth pulp nerves of symptomatic teeth associated with pulpitis." (PMID 31071917, 2019).
retinal diseases (2 papers, 2018). "The role of TRPV4 in other retinal diseases has not been explored." (PMID 30143574, 2018).
retinal edema (2 papers, 2019 to 2024). "This increased expression of TRPV4 is associated with the aggravation of ischemic conditions and the development of retinal edema in the RVO model." (PMID 39517820, 2024). "The role of TRPV4 may also extend to other types of retinal edema." (PMID 31048895, 2019).
rheumatoid arthritis (2 papers, 2012 to 2024). A chronic, systemic autoimmune disorder characterized by inflammation in the synovial membranes and articular surfaces. "On the other hand, activation of TRPV4 reduces IL1-induced secretion of IL8 in synoviocytes from patient with rheumatoid arthritis and in human esophageal epithelial cells." (PMID 22843691, 2012).
solar keratosis (2 papers, 2021). "Contradictory to our results, another research group detected a downregulation of TRPV4 in specific NMSC, as Bowen’s disease (BD), solar keratosis (SK), and also BCC and SCC." (PMID 34199609, 2021).
synovitis (2 papers, 2021 to 2022). Inflammation of a synovial membrane. "According to our results, TRPV4 appears to be a unique therapeutic target for alleviating OA by relieving synovitis." (PMID 36552524, 2022). "Increased articular cartilage grades and synovitis scores were also observed in TRPV4-KO MIA rats (articular cartilage grade: P < 0.001, synovitis score: P < 0.001)." (PMID 34396019, 2021). "However, whether TRPV4 participates in M1 synovial macrophage polarization by affecting ROS generation and the role of TRPV4 in synovitis remains to be explored." (PMID 36552524, 2022).
abdominal aortic aneurysm (1 paper, 2022). Enlargement and ballooning of the vessel that supplies arterial blood to the abdomen, pelvis and legs. "For example, GSK2193874 is a TRPV4 blocker with an oral activity which inhibits the formation of the abdominal aortic aneurysm by reducing the activation of smooth muscle cells and the migration of neutrophils across cells." (PMID 35813831, 2022).
adenovirus infection (1 paper, 2015). "48-hr adenovirus infection dramatically increased TRPV4 protein expression in cell membrane." (PMID 26177349, 2015). "As expected, while TRPV4 was up-regulated by adenovirus infection in mice, the increased systolic BP and diastolic BP were not inhibited significantly by berberine." (PMID 26177349, 2015).
age (1 paper, 2016). A temporal measurement of the time period elapsed since an identifiable point in the life cycle of an organism. "The results of this study has led us to ask if inhibition of TRPV4 through pharmacologic means can similarly provide protection from age-related OA pathogenesis." (PMID 27388701, 2016).
anaemia (1 paper, 2015). "Basal haemoglobin and haematocrit levels were also decreased in naïve TRPV4 KO mice, relative to WT controls, indicative of basal anaemia." (PMID 26064477, 2015).
aortic aneurysm (1 paper, 2022). A ruptured aneurysm located in the wall of the proximal portion of the descending aorta proceeding from the arch of the aorta. "The mechanistic signaling involving the concurrent activation of Panx1, P2X/Y, and TRPV4 channels could account for the slow and sustained development of chronic aortic pathologies, i.e., aortic aneurysms." (PMID 35315432, 2022).
autosomal recessive dHMN (1 paper, 2016). "Two heterozygous variants were detected in genes associated with autosomal dominant spinal muscular atrophy and CMT2 (BICD2 and TRPV4) and one homozygous variant was detected in SIGMAR1, a gene associated with autosomal recessive dHMN and juvenile ALS." (PMID 27629094, 2016).
bacteremia (1 paper, 2021). "In this mouse model using a virulent pneumococcal strain, TRPV4 KO mice were more susceptible to development of bacteremia, although all mouse strains were colonized equally." (PMID 34804016, 2021). "Although bacteremia was detected at the same frequency in all mouse strains when the dose of inoculum was increased, TRPV4 KO mice showed the highest density of bacteremia." (PMID 34804016, 2021). "Even by low-dose challenge, TRPV4 KO mice frequently developed bacteremia when the mice were precedingly infected with influenza virus." (PMID 34804016, 2021). "The density of bacteremia in TRPV4 mice was significantly higher than that of wild type by Kruskal–Wallis test (p = 0.028)." (PMID 34804016, 2021). "On the other hand, a significantly higher ratio of bacteremia was observed in TRPV4 KO mice (15 out of 31 mice, 48.4%) compared with wild-type (3 out of 20 mice, 15%) and with TRPV1 KO mice (4 out of 14 mice, 28.6%) by high-dose inoculation." (PMID 34804016, 2021). "In the mono-infection model, the incidence of bacteremia significantly increased among TRPV4 KO mice by high-dose challenge." (PMID 34804016, 2021). "Both the density and the incidence of bacteremia were significantly higher in TRPV4 mice than in wild-type mice (p = 0.036)." (PMID 34804016, 2021).
bacterial pneumonia (1 paper, 2021). Acute infection of the lung parenchyma caused by bacteria (e.g., Streptococcus pneumoniae, Haemophilus influenzae, Chlamydia pneumoniae, Mycoplasma pneumoniae, and Legionella pneumophila). "The TRPV4 channel may protect from bacterial pneumonia caused by Pseudomonas aeruginosa through mitogen-activated protein kinase (MAPK) switching." (PMID 34804016, 2021).
benign meningioma (1 paper, 2021). A grade I, slowly growing meningioma. "In conclusion, in this study, we report high AQP4 expression which was significantly correlated with TRPV4 expression in benign meningiomas." (PMID 33538957, 2021).
brain cancer (1 paper, 2022). A primary or metastatic malignant neoplasm affecting the brain. "In contrast, TRPV4 and TRPC1 are other TRP channels that have consistently been shown to play a pro-tumorigenic role in brain cancer." (PMID 36497413, 2022). "TRPV4 is another potential binding partner for EGFR, ANO1, and IP3R, although this has yet to be demonstrated in brain cancer cells." (PMID 36497413, 2022).
cartilage disease (1 paper, 2021). Softening and degeneration of the CARTILAGE. "In addition to providing new mechanistic understanding of this pathway, this study identifies TRPV4 as a potential therapeutic target and demonstrates that pharmaceutical activation of this protein could regulate inflammation and other IFT-dependent pathways involved in cartilage disease." (PMID 33395574, 2021).
cataract (1 paper, 2023). Partial or complete opacity of the crystalline lens of one or both eyes that decreases visual acuity and eventually results in blindness. "It is too early to propose therapeutic implications, and yet we feel inclined to think about the possibility that mishandling of Ca2+ by a dysfunctional TRPV4-Cx43 HCh axis may have a role in the genesis of certain chronic conditions, like cataracts." (PMID 36909173, 2023).
cholestasis (1 paper, 2021). Impairment of the bile flow caused by obstruction within the liver, or outside the liver in the bile duct system. "Next we addressed the role of keratinocyte-TRPV4 in cholestatic itch and whether LPC and miR-146a function as pruritogens in a cholestasis disease-relevant context." (PMID 33819485, 2021). "TRPV4 in skin keratinocytes was essential for LPC-induced itch and itch in mice with cholestasis." (PMID 33819485, 2021).
chronic lung disease (1 paper, 2022). According to the definitions of the American and British Thoracic Societies, including pulmonary functional tests, X-rays, and CT scans for items such as fibrosis, bronchiectasis, bullae, emphysema, nodular or lymphomatous abnormalities. "Moreover, several studies show a modulatory role of hypoxia on TRPV4 channel function, which occurs, not only in a variety of chronic lung diseases, but also in other organ systems and related diseases." (PMID 35883510, 2022). "Previous studies have shown that prolonged hypoxia exposure occurring particularly, but not exclusively, in a variety of chronic lung diseases, increases TRPV4 activity in pulmonary arterial smooth muscle cells (PASMC)." (PMID 35883510, 2022).
chronic pancreatitis (1 paper, 2022). A chronic inflammatory process causing damage and fibrosis of the pancreatic parenchyma. "Thus, high pressure within the pancreas stimulates Piezo1 channel opening, and subsequent activation of TRPV4 leads to stellate cell activation and pressure-induced chronic pancreatitis and fibrosis." (PMID 35451372, 2022). "It will be interesting to evaluate Piezo1 and TRPV4 in stellate cells of patients with chronic obstructive pancreatitis and to determine if administration of a Piezo1 or TRPV4 blocker can block or reverse obstructive chronic pancreatitis and fibrosis in humans." (PMID 35451372, 2022). "If pathological effects of Piezo1 (high-pressure–induced stellate cell activation and fibrosis) require TRPV4 channels, we would expect that mice lacking TRPV4 would be protected against pressure-induced chronic pancreatitis and fibrosis." (PMID 35451372, 2022).
cognitive decline (1 paper, 2025). "Collectively, these findings implicate TRPV4 dysregulation as a key driver of synaptic dysfunction and cognitive decline." (PMID 41341920, 2025). "This suggests that excessive TRPV4 activity may negatively influence hippocampal network remodeling and long-term potentiation (LTP), thereby accelerating age-associated cognitive decline." (PMID 41341920, 2025).
congenital hydrocephalus (1 paper, 2022). Hydrocephalus that is present at birth. "Transient receptor potential cation channel subfamily V member 4 (TRPV4) is an ion channel protein that is recently being studied as a potential target for congenital hydrocephalus (CH) of neonates." (PMID 36406122, 2022).
Constipation (1 paper, 2023). Infrequent or difficult evacuation of feces. "Here we investigated how changes in TRPV4 expression in colonic epithelium from healthy subjects and patients with chronic constipation were related to constipation symptoms and populations of mucosal-adhesive intestinal bacteria." (PMID 36639736, 2023). "Next, we examined the relationship between constipation symptoms and TRPV4 expression and bacteria adhering to the rectal mucosa using clinical information and human specimens from constipation patients and healthy subjects." (PMID 36639736, 2023). "We also investigated TRPV4 expression in colon epithelium from patients with constipation." (PMID 36639736, 2023).
corneal diseases (1 paper, 2016). "The present results suggest that chemical blocking of TRPV4 channel activation could be beneficial in treating inflammation-based corneal diseases." (PMID 28030558, 2016).
Darier disease (1 paper, 2020). Darier disease (DD) is a keratinization disorder characterized by the development of keratotic papules in seborrheic areas and specific nail anomalies. "Dysregulated epidermal calcium gradients can also produce dual expression of K14 and K10, such as in the skin blistering disorders Hailey-Hailey disease and Darier disease, and in TRPV4 KO mice which suffer defective tight junction formation." (PMID 33125436, 2020).
demyelination diseases (1 paper, 2018). "This study reveals a new mechanism by which TRPV4-mediated inflammation is involved in myelin sheath damage in the CNS and may provide a possible therapeutic target for demyelinating diseases." (PMID 30455633, 2018). "Therefore, TRPV4 channels may represent a promising novel target to ameliorate neuroinflammation-mediated demyelination diseases." (PMID 30455633, 2018).
dengue (1 paper, 2018). "Consequently, targeting of TRPV4 reduces infectivity of dengue, hepatitis C and Zika viruses." (PMID 29899501, 2018).
dilated cardiomyopathy (1 paper, 2024). Cardiomyopathy which is characterized by dilation and contractile dysfunction of the left and right ventricles. "Recent data coming from experimental models and patients with dilated cardiomyopathy have confirmed that TRPV4 channels contribute to impaired cardiac contractility and HF progression by inducing abnormal cytosolic Ca2+ dynamics in CM." (PMID 38338818, 2024).
ductal carcinoma in situ (1 paper, 2025). "High-grade ductal carcinoma in situ (DCIS) and invasive ductal cancer (IDC) ROIs clearly exhibit plasma membrane association of TRPV4." (PMID 40256993, 2025).
duodenal ulcer (1 paper, 2022). An ulcer in the duodenal wall. "Here, we found that TRPV4 is highly expressed in children with duodenal ulcer and has good diagnostic value through specimens of children with duodenal ulcer, and animal experiments have proved that TRPV4 is also highly expressed in duodenal ulcer mice." (PMID 35028313, 2022). "In our research, we found that TRPV4 is significantly highly expressed in children with duodenal ulcer and has a good diagnostic value." (PMID 35028313, 2022). "Therefore, this study provides the diagnostic and therapeutic value of TRPV4 in children with duodenal ulcer." (PMID 35028313, 2022). "In addition, receiver operating characteristic curve (ROC) analysis showed that TRPV4 had a good diagnostic value in children with duodenal ulcer." (PMID 35028313, 2022). "In summary, these results indicate that TRPV4 is involved in the occurrence and development of duodenal ulcer." (PMID 35028313, 2022). "In summary, the present study demonstrated that TRPV4 is highly expressed in patients with duodenal ulcer." (PMID 35028313, 2022). "Animal models prove that TRPV4 can affect intestinal permeability, thereby promoting further infiltration of inflammatory factors and further lead to the development of duodenal ulcer." (PMID 35028313, 2022). "The results suggested that TRPV4 is significantly highly expressed in the tissues of children with duodenal ulcer." (PMID 35028313, 2022). "In the present study, we tested the expression of TRPV4 in duodenal ulcers in children." (PMID 35028313, 2022). "In a word, we used clinical samples of children with duodenal ulcer revealed high expression of TRPV4, and the mouse model of duodenal ulcer proved that TRPV4 promotes the occurrence and development of duodenal ulcer by affecting intestinal epithelial permeability." (PMID 35028313, 2022). "We also investigated whether TRPV4 can regulate the epithelial barrier in mouse model of duodenal ulcer." (PMID 35028313, 2022). "But whether TRPV4 is involved in mediating duodenal ulcers in children remains unclear." (PMID 35028313, 2022). "Here, we found that the expression of TRPV4 was significantly increased in children with duodenal ulcers, and it may affect the infiltration of inflammatory factors by affecting the permeability of intestinal epithelium, thereby affecting the development of duodenal ulcer." (PMID 35028313, 2022). "In the present study, we found that neither the TRPV4 agonist GSK1016790A nor the TRPV4 antagonist HC067047 altered inflammatory factors in duodenal ulcer mice tissue." (PMID 35028313, 2022). "In order to prove whether the expression of TRPV4 is different in children with duodenal ulcer, we collected tissue samples from children with duodenal ulcer (DU) and those with nonulcer (Ctrl) and detected the expression of TRPV4 in children with duodenal ulcer through immunohistochemistry." (PMID 35028313, 2022). "But, in the duodenal tissue of duodenal ulcer mice, although the expression of TNF-α increased, TRPV4 did not affect the expression of TNF-α in the tissue." (PMID 35028313, 2022).
dyslipidemia (1 paper, 2021). "An in vivo study of mice models by Lakk in 2017 demonstrates that dyslipidemia causes dysregulation of these TRPV4 channels and subsequent glial cell damage." (PMID 33828528, 2021). "TRPV4, a nonselective cation channel that responds to cell swelling has been implicated as a potential source for retinal damage in dyslipidemia states." (PMID 33828528, 2021).
dyspepsia (1 paper, 2017). An uncomfortable, often painful feeling in the stomach, resulting from impaired digestion. "HP infection‐dependent DNA methylation suppressed TRPV4 expression in human gastric epithelia, suggesting that TRPV4 methylation may be involved in HP‐associated dyspepsia." (PMID 27687509, 2017).
ependymoma (1 paper, 2021). A WHO grade II, slow growing tumor of children and young adults, usually located intraventricularly. "TRPV2, TRPV4, and TRPA1 were expressed to similar levels across the two ependymoma subgroups." (PMID 33477420, 2021).
familial episodic pain syndrome (1 paper, 2025). "Notably, the S4-S5 linker appears to be a hot-spot for mutations in several TRP channels, including TRPV3 (congenital Olmsted syndrome), TRPV4 (skeletal dysplasia, motor/sensory neuropathies), TRPA1 (familial episodic pain syndrome), and TRPML1 (mucolipidosis type IV)." (PMID 41005473, 2025).
Fever (1 paper, 2025). Body temperature elevated above the normal range. "However, Wang and colleagues found that TRPV4 was increased in the hypothalamus of LPS-induced pyrexia in rats, which led to an increase in calcium influx and then upregulation of cAMP expression to mediate the fever process." (PMID 40356990, 2025). "By replicating the zebra fish fever model, it was found that TRPV1, TRPV4, and PGE2 co-regulated the development of fever, and the decreased expression of TRPV4 contributed to the generation of fever." (PMID 40356990, 2025). "Compared with the NG, the mRNA expressions of TNF-α, IL-6, IL-1β, NF-κB, TRPV4, and HSP70 in the MG were significantly upregulated (P < 0.01), indicating that the expression of mRNA was enhanced under fever conditions." (PMID 40356990, 2025).
gastric adenocarcinoma (1 paper, 2022). "In gastric adenocarcinoma tissues, the protein level of TRPV4 is increased, and the higher TRPV4 expression, the deeper the tumor invasion and lymph node metastasis, and the higher the TNM stage." (PMID 35558077, 2022).
gastroesophageal reflux disease (1 paper, 2024). A chronic disorder characterized by reflux of the gastric and/or duodenal contents into the distal esophagus. "As the pH necessary to open the channel is lower than physiological levels in most compartments, the pH activation of TRPV4 is mainly relevant in conditions of acid-induced ALI, as occurs through occupational exposure or in patients suffering from gastroesophageal reflux disease (GERD)." (PMID 39451235, 2024).